MRPL9 (mitochondrial ribosomal protein L9)
Synonyms: L9mt; bL9m
Tractability: Small molecule: a structure with a bound ligand is known. PROTAC: ubiquitination databases record sites on it; its protein half-life has been measured.
Target class: Other cytosolic protein
Gene: Protein-coding gene on chromosome 1 (151,759,647 to 151,763,496, reverse strand). Ensembl gene ENSG00000143436.
Subcellular location: Mitochondrion
Subcellular location (Human Protein Atlas): Mitochondria
Pathways (Reactome):
Metabolism of proteins: Mitochondrial ribosome-associated quality control; Mitochondrial translation elongation; Mitochondrial translation initiation; Mitochondrial translation termination
Gene Ontology:
Molecular function: protein binding; RNA binding; structural constituent of ribosome
Biological process: mitochondrial translation; translation
Cellular component: mitochondrial large ribosomal subunit; mitochondrion; mitochondrial inner membrane; mitochondrial ribosome; ribosome
Genetic constraint (gnomAD): Loss-of-function variants: 24 observed, 24.84 expected, observed/expected ratio (o/e) 0.97, 90% interval 0.7 to 1.36. The upper end of that interval is the gene's LOEUF score, 1.36, which puts it in group 5 of 6, group 1 being the genes least tolerant of losing a copy. Missense variants: 354 observed, 327.17 expected, observed/expected ratio (o/e) 1.08, 90% interval 0.99 to 1.18. Synonymous variants: 150 observed, 136.19 expected, observed/expected ratio (o/e) 1.1, 90% interval 0.96 to 1.26.
Homologues: Orthologues: chimpanzee MRPL9 (99% identical), macaque MRPL9 (94% identical), pig MRPL9 (85% identical), guinea pig MRPL9 (82% identical), mouse Mrpl9 (80% identical), dog MRPL9 (80% identical), rat mrpl9 (78% identical), tropical clawed frog MRPL9 (53% identical), zebrafish mrpl9 (46% identical), Drosophila melanogaster mRpL9 (26% identical), Caenorhabditis elegans mrpl-9 (21% identical).
Diseases named in the same sentence as MRPL9 in open-access papers:
MRPL9 is named in the same sentence as 11 diseases in open-access papers, as found by Europe PMC text mining. Sharing a sentence is not in itself a finding about the gene and the disease. The quoted sentences say what the papers report.
breast carcinoma (3 papers, 2020 to 2025). "Despite having received less attention in oncology research, MRPL9 has been discovered to have an oncogenic characteristic in breast cancer." (PMID 37502362, 2023). "A new logistic regression model to classify breast cancer tumor samples based on microarray expression data was introduced in some papers, which illustrated that those genes, such as MRPL9, exhibit oncogenic characteristics and may be potential breast cancer predictors." (PMID 33238645, 2020). "MRPL9 is a component of the mtLSU and is upregulated in many types of cancer, including lung cancer, HCC, and breast cancer." (PMID 39859078, 2025).
hepatocellular carcinoma (3 papers, 2024 to 2026). A malignant tumor that arises from hepatocytes. "In lung cancer and hepatocellular carcinoma, MRPL9 overexpression is associated with poor survival and recurrence, and knockdown in an in vitro cell model inhibited pro-metastatic capabilities such as migration, spheroid formation, and proliferation." (PMID 39354291, 2024). "MRPL9 was found to be associated with chemoresistance pathways in hepatocellular carcinoma, including cell cycle, mismatch repair, and spliceosome signalling." (PMID 39354291, 2024). "In hepatocellular carcinoma, MRPL9 was used in a two gene prognostic model that could predict prognosis, immune infiltration, and chemoresistance." (PMID 39354291, 2024).
liver cancer (3 papers, 2022 to 2024). An epithelial or non-epithelial malignant neoplasm that arises from the liver. "MRPL9, a nuclear gene encoding protein component in mitochondrial ribosomes, is highly expressed in liver cancer and associated with the proliferation and migration of HCC." (PMID 39041652, 2024). "It has been reported that MRPL9 is highly expressed in liver cancer and is associated with poor prognosis, and knockdown of MRPL9 inhibits the proliferation and migration of liver cancer cells." (PMID 36233293, 2022). "It has been reported that MRPL9 is highly expressed in liver cancer and promotes cell proliferation and migration, but it has not been reported in PTC." (PMID 36233293, 2022). "Cell cycle disruption could lead to infinite proliferation, which might play a critical role in liver cancer and a promising therapeutic target, suggesting that MRPL9 may function a critical role in the tumorigenesis of HCC." (PMID 36684217, 2022).
lung carcinoma (3 papers, 2024 to 2025). "Immunohistochemical (IHC) experiments further validate the high expression of MRPL15 in NSCLC and confirm its potential as a prognostic marker.The expression of MRPL9 is upregulated in lung cancer tissues and is associated with OS and RFS in patients." (PMID 40371222, 2025). "Knocking down MRPL9 significantly reduces the proliferation, colony formation, and migration capabilities of lung cancer cells." (PMID 40371222, 2025). "Therefore, repurposing them to target MRPs, such as MRPL13 and MRPL9 in aggressive lung cancer is a promising area of future research." (PMID 39354291, 2024). "MRPL9 was found to modulate c-MYC transcription, which alters ZEB1 expression to regulate the expression of e-cadherin in lung cancer." (PMID 39354291, 2024). "In A549 cells, the expression of MRPL9 remains unchanged after c-MYC is knocked down, suggesting that MRPL9 may promote lung cancer metastasis by regulating c-MYC transcription, thereby affecting the expression of migration-related molecules." (PMID 40371222, 2025). "Further research indicates that MRPL9 may promote lung cancer progression by regulating the transcription of c-MYC, especially in lung cancer tissues with high c-MYC expression." (PMID 40371222, 2025).
liver disease (1 paper, 2022). "Further, we focused on MRPL9 and explored the alterations of serum MRPL9 in patients with hepatic disease and healthy volunteers, thus confirming the diagnostic function." (PMID 36684217, 2022). "Enzyme-linked immunosorbent assay (ELISA) measured serum mitochondrial ribosomal protein L9 (MRPL9) levels in liver disease patients and normal individuals." (PMID 36684217, 2022). "Uniformly, the serum concentration of MRPL9 in HCC patients was significantly enhanced compared with early liver diseases and healthy individuals." (PMID 36684217, 2022).
lymph node metastasis (1 paper, 2022). "The high MRPL9 expression group was associated with a higher degree of TNM progression, extrathyroidal extension and lymph node metastasis (p ≤ 0.05)." (PMID 36233293, 2022).
retinitis pigmentosa (1 paper, 2018). Retinitis pigmentosa (RP) is an inherited retinal dystrophy leading to progressive loss of the photoreceptors and retinal pigment epithelium and resulting in blindness usually after several decades. "At least three other MRP genes; MRPL9, MRPL23, and MRPL39 map to genomic regions associated with retinitis pigmentosa indicating the importance of this pathway in retinal pathology." (PMID 29739359, 2018).
cancer (5 papers, 2019 to 2025). A tumor composed of atypical neoplastic, often pleomorphic cells that invade other tissues. "High MRPL9 expression is known to be associated with decreased e-cadherin expression, which is essential for cancer-specific EMT." (PMID 39354291, 2024). "The ROC curve analysis showed that MRPL9 was superior to the other two normal serum biomarkers (AUC = 0.867) in differentiating HCC from non-cancer subjects." (PMID 36684217, 2022). "Together, these studies suggest MRPL9 may play a key role in aggressive cancer phenotypes and could be a viable therapeutic target." (PMID 39354291, 2024). "The results showed that MRPL9 was highly expressed in PTC cancer tissues." (PMID 36233293, 2022). "Bioinformatics files illustrated that MRPL9 levels have increased in most cancers, including HCC." (PMID 36684217, 2022). "To date, there are limited reports on MRPL9 and MRPL37 in cancer, and our understanding of their roles in the disease is still limited." (PMID 39859078, 2025). "In this study, GGCT and MRPL9 were shown to be involved in regulating the biological behavior of PTC tumor cells and promoting the further development of cancer, suggesting that GGCT and MRPL9 may serve as potential biomarkers." (PMID 36233293, 2022).
tumor (4 papers, 2021 to 2024). "The serum MRPL9 was associated with tumor size and distant tumor metastasis." (PMID 36684217, 2022). "In vitro experiments have found that upregulated MRPL9 can significantly promote tumor proliferation, metastasis, and interfere with the cell cycle by advancing the transition of G1/S phase." (PMID 39487553, 2024). "Given the increased level of serum MRPL9 in HCC patients, we further determined the correlation between MRPL9 and different clinicopathological factors, including gender, age, tumor size, CNLC stage and HCC diagnostic markers including AFP, Ferritin." (PMID 36684217, 2022). "To elucidate the role of MRPL9 in HCC, we transfected overexpressed MRPL9 plasmid into Huh7 and HepG2 cells and found that upregulated MRPL9 could significantly promote tumor proliferation, metastasis and interfere cell cycle by promoting the transition of G1/S phase." (PMID 36684217, 2022). "Finally, the effects of MRPL9 and GGCT on tumor growth and metastasis were further investigated in vivo." (PMID 36233293, 2022).
MRPL9 also shares sentences with these, for which no sentence is quoted: Papillary Thyroid Cancer (2 papers); thyroid cancer (2).